TNF (tumor necrosis factor)
Diseases named in the same sentence as TNF in open-access papers (continued):
Sharing a sentence is not in itself a finding about the gene and the disease.
periodontitis (continued). "Anticytokine therapy for periodontal diseases especially targets proinflammatory cytokines, that is, TNF-α, IL-1, and IL-6, because these are essential for the initiation of the inflammatory immune reaction and are produced for prolonged periods in periodontitis." (PMID 20407652, 2009). "In the mouse periodontitis model, local administration of GaELNs significantly reduces gingival inflammation and alveolar bone resorption, and decreases the expression of inflammatory mediators (TNF-α, IL-12, CXCL-12, and CXCL-5) through activation of the PHGDH/PI3K/Akt signaling pathway." (PMID 41484074, 2026). "Researchers further conducted in vivo experiments with periodontitis mouse models and reported that F. nucleatum OMV-treated periodontitis model mice presented greater numbers of osteoclasts, more widespread alveolar bone damage, and significant increases in the levels of IL-1β, IL-6, and TNF-α." (PMID 41208888, 2025). "The pathogenesis of periodontitis is primarily driven by dysbiotic microbial communities that initiate an inflammatory cascade involving the upregulation of cytokines such as interleukin-6 (IL-6), tumor necrosis factor-alpha (TNF-α), and nuclear factor kappa B (NF-κB)." (PMID 41150759, 2025). "The pathogenesis of periodontitis involves a dysbiotic oral microbiota triggering a sustained host immune response, leading to elevated systemic levels of pro-inflammatory cytokines such as tumor necrosis factor-alpha (TNF-α), interleukin-6 (IL-6), and C-reactive protein (CRP)." (PMID 41030757, 2025). "Its ability to down-regulate cytokines such as IL-1β, TNF-α, and IL-6, its interaction with IL-17 signaling, and its role in controlling osteoclast differentiation and alveolar bone resorption highlight its broader relevance in the pathogenesis of periodontitis." (PMID 41289041, 2025). "Furthermore, experimental periodontitis exacerbates inflammation not only by increasing the stromal vascular fraction (SVF) in AT to promote pro-inflammatory cytokine (TNF-α and IL-6) secretion, but also by altering circulating levels of adipokines such as resistin, adiponectin, and leptin." (PMID 41246338, 2025). "Importantly, ordinal regression analyses confirmed that higher salivary TNF-α and TMAO levels were significantly associated with higher odds of periodontitis, even after adjusting for age, reinforcing their relevance as potential indicators of periodontal disease risk." (PMID 40131489, 2025). "This novel model more accurately mimicked clinical UC features, especially the alternating active and remission phases, and revealed that periodontitis may exacerbate UC, likely through elevated inflammatory factors (TNF-α, IL-6) and gut microbiota alterations." (PMID 40462053, 2025). "Future studies should focus on understanding how carriers of these specific HLA-DRB1 alleles may exhibit increased production of pro-inflammatory cytokines, including TNF-α, IL-1β, and IL-6, all of which are central to the tissue destruction seen in periodontitis." (PMID 40283738, 2025). "Importantly, TNF-α concentrations are correlated with some periodontitis parameters." (PMID 40076424, 2025). "A cross-sectional study revealed increased serum levels of TNF-α and IL-6 in patients with cognitive impairment and periodontitis, which suggested that the presence of systemic inflammation in periodontitis patients may affect the progression of neurodegenerative diseases." (PMID 40933993, 2025). "To investigate whether FMT can improve intestinal barrier function and reduce inflammation in periodontitis mice, we further analyzed the colonic expression of tight junction proteins, inflammatory cytokines (IL-6, TNF-α), and MUC2 after different treatment conditions." (PMID 41040884, 2025).
periodontitis (continued). "Mechanistic studies further reveal that chronic periodontitis exhibits pathophysiological synergism with cardiovascular disease determinants mediated by circulating mediators including interleukin-6 (IL-6), tumor necrosis factor-alpha (TNF-α), and high-sensitivity C-reactive protein (hsCRP)." (PMID 40722812, 2025). "She concluded that the placental extract group could be used as a local drug delivery system in combination with SRP for the treatment of periodontitis due to its potential to decrease inflammation by decreasing the inflammatory cell mass and TNF-α immune expression." (PMID 38975382, 2024). "Proinflammatory substances like TNF-α, IL-6 and IL-1 aresecreted by activated microglia, which also use TLRs to initiate innate immune responses.Understanding the connection between glaucoma and periodontitis requires an understanding of inflammation and innate immunity." (PMID 39917226, 2024). "We can speculate that the increases in TNF-α, IL-1α, CXCL1, CCL2, and Th17 responses following testosterone GAHT therapy could increase inflammation in periodontal tissues, potentially elevating periodontitis risk." (PMID 39917660, 2024). "As the concentration of serum TNF-a was significantly higher in rats with periodontitis and T2DM compared to those with T2DM only, the authors posited that periodontitis and the associated production of proinflammatory cytokines might contribute to these findings." (PMID 39337292, 2024). "On day 7 after periodontitis induction and treatment administration, blood was drawn from the inferior vena cava, totaling 10 mL, to obtain blood serum for determining the levels of proinflammatory cytokines TNF-α, IL-1β, and anti-inflammatory cytokines IL-10, IL-13 through ELISA examination." (PMID 39539670, 2024). "Salivary and plasma levels of IL-1β, IL-6, and TNF-α increase with periodontal disease severity, and plasma MMP-8 and MMP-9 levels decrease after non-surgical periodontal treatment events, supporting the theory of periodontitis causing increased systemic inflammation." (PMID 38672972, 2024). "Furthermore, resveratrol decreased TNF-α, IL-1, and IL-6 levels in rats with periodontitis." (PMID 39456522, 2024). "Therefore, we designed the model mimicking bone loss in periodontitis by using TNF-α stimulated human osteoblasts and found that 50 ng/mL of TNF-α could significantly upregulate RANKL expression at 24 and 48 hours." (PMID 37562430, 2024). "Finally, we have compared peak breadth distribution within genes positioned by H3K4me3, and we noted a decrease in the average breadth as well as more ‘sharp–narrow’ peaks in patients with NMOSD and periodontitis, which corresponds with TNF-preactivated and IL-10-stimulated neutrophils." (PMID 38745328, 2024). "Inflammatory mediators such as C-reactive protein (CRP), interleukin-6 (IL-6), and tumor necrosis factor-alpha (TNF-α) are elevated in both periodontitis and metabolic syndrome, suggesting a bidirectional relationship where each condition may exacerbate the other." (PMID 39338063, 2024). "Inflammatory factors such as TNF-α and IL-1β in the inflammatory environment activate the NF-κB signalling pathway, while the NF-κB signalling pathway promotes the expression of these inflammation-related factors, creating a vicious cycle that exacerbates the development of chronic periodontitis." (PMID 37724115, 2023). "Periodontitis is one of the diabetic complications that induces the production of inflammatory cytokines such as interleukin-1 (IL-1), interleukin-6 (IL-6), interleukin-8 (IL-8), interleukin-17 (IL-17), and tumor necrosis factor-α (TNFα) and reduced anti-inflammatory cytokines under hyperglycemia." (PMID 37408216, 2023). "Furthermore, the results of this study confirmed the interactive relationship between TNF-α and caspase-1 salivary levels, which may play a considerable role in triggering the processes that lead to chronic inflammation in clinical periodontitis." (PMID 36794778, 2023).
periodontitis (continued). "Moreover, these cytokines like TNF-α and IL-1β, which are produced from local periodontitis area, may reach the brain, and promote the AD pathology." (PMID 37635786, 2023). "Of the studies included in this systematic review, four studies evaluated the levels of the pro-inflammatory cytokines IL-1β, IL-6, and TNF-α, the anti-inflammatory cytokine IL-10, and the matrix metalloproteinase-8 (MMP8), which is associated with the clinical manifestation of periodontitis." (PMID 37109642, 2023). "The precise role of TNF-α in periodontitis is still unknown." (PMID 36794778, 2023). "Thus, selected salivary biomarkers showed high sensitivity and specificity in the diagnosis of periodontitis and distinguishing it from periodontal health at the proposed cut-off points (128.163 pg/ml of proinflammatory cytokines [TNF-α] and 1.626 ng/ml of caspase-1)." (PMID 36794778, 2023). "Endoplasmic reticulum (ER) stress was found to participate in reducing the osteogenic differentiation ability of PDLSCs in the inflamed microenvironment induced by tumor necrosis factor-α (TNF-α), which indicated ER stress could promote the damage of periodontal tissue in periodontitis." (PMID 36894905, 2023). "Also, TNF levels were reduced in response to periodontitis treatment." (PMID 36845132, 2023). "However, the exact mechanism that produces the TNF-α and IL-1β in periodontitis is still unclear." (PMID 35830121, 2022). "Therefore, we hypothesized that bLF administration may be effective in inhibiting the pathological progression of RA, in which TNF-α plays a key role in the development and progression of inflammation and bone destruction, such as periodontitis." (PMID 35148358, 2022). "Some reports have explained that a decrease in the levels of TNF-a, IL-1b, and IL-17 in the periodontal pockets of patients with periodontitis is observed following the treatment with the probiotic strain of L Lactobacillus reuteri, which may carry clinical significance." (PMID 35631603, 2022). "The inflammatory markers Interleukin-1 alpha(IL-1α), Tumor Necrosis Factor-alpha (TNF-α), and high sensitive C reactive protein (hsCRP), the hematological analyses, and the histological probes showed a similar and reproducible periodontal inflammation for the molar induced periodontitis model." (PMID 35625362, 2022). "Furthermore, the components of saliva may be affected by gingival bleeding, as the levels of TNF-α in saliva and serum are similar and are increased in patients with periodontitis." (PMID 35200250, 2022). "The periodontitis symptoms of mice in the F. nucleatum OMVs + ligation group were more serious than those of mice in the simple ligation group, with more osteoclasts and more inflammatory factors (IL-1β, IL-6, and TNF-α) being observed in their gingival tissues." (PMID 35391731, 2022). "Our previous work demonstrated that exosomes from tumor necrosis factor (TNF)-α-primed human gingiva-derived MSCs (GMSCs) could be a therapeutic tool against periodontitis, and that TNFα-inducible exosomal miR-1260b is essential for the inhibition of alveolar bone loss." (PMID 36531939, 2022). "Notably, TNF-α is also upregulated in periodontitis, a high prevalence inflammatory disease." (PMID 35137648, 2022). "However, it remains unclear how sTNF-R is related to inflammatory oral diseases, such as periodontitis, in which TNF-α is involved in the development of inflammation." (PMID 35200250, 2022). "Moreover, an increased level of TNF-α in offspring from mothers with periodontitis may confirm previous evidence that low-grade systemic inflammation develops early in the process of T2DM." (PMID 35269617, 2022). "Therefore, in order to confirm the evidence for the inhibition of inflammatory infiltration, the production of the representative proinflammatory cytokines IL-6, IL-1, and TNF of periodontitis in serum isolated from the blood of periodontitis-induced rats was evaluated." (PMID 36145616, 2022).
periodontitis (continued). "In an effort to explore possible downstream targets by which miR-146a may contribute to the pathobiology of disease, the levels of the main pro-inflammatory cytokines such as TNF-α, IL-1β, and IL-6 were studied in patients with chronic and aggressive periodontitis." (PMID 34645448, 2021). "Similarly, anti-TNF treatment has shown promising results in periodontitis." (PMID 33778080, 2021). "Besides, the existence of elevated cytokines expression comprising pro‐inflammatory and regulatory cytokines such as IL‐1β, interferon (IFN)‐γ, IL‐1 receptor antagonist (RA), IL‐4, IL‐6, IL‐10, IL‐12, TNF‐α, and induced protein (IP)‐10, lead the way to periodontitis’ inflammatory process." (PMID 34272761, 2021). "Surprisingly, in an animal model of both periodontitis and asthma, researchers reported that periodontitis in asthmatic mice resulted in reduced migration of eosinophils, lymphocytes, and macrophages into the airways, reduced levels of IL-4 and TNF-α, and decreased mucus production." (PMID 34765263, 2021). "Furthermore, periodontitis induces systemic inflammation and pro-inflammatory cytokines can activate endothelial cells that express receptors for TNF-α and IL-1, which, in turn, signal to the perivascular macrophages located immediately adjacent to cerebral endothelial cells." (PMID 35153869, 2021). "Furthermore, animal studies have provided some evidence to show that miR-146a exerts anti-inflammatory impacts in periodontitis through inhibiting the expressions of the pro-inflammatory cytokines such as tumor necrosis factor-alpha (TNF-α), interleukin-1β (IL-1β), and IL-6 in periodontal tissue." (PMID 34645448, 2021). "Interestingly, high levels of TNF-a, which activates pathways that culminate in the destruction of periodontal connective tissue and alveolar bone resorption, were detected in diseased sites of individuals with severe periodontitis." (PMID 34680779, 2021). "Pro-inflammatory cytokines, such as IL-1β, IL-6, and TNF-α, are representative co-related molecules involved in the induction and regulation of the inflammatory cascade in systemic inflammatory disorders, including RA, periodontitis, and gut inflammatory diseases." (PMID 33716675, 2021). "The polymorphisms of IL-2 and TNF-α of Th1 cytokine family may be associated with the pathogenesis or the prevention of periodontitis risk, while the polymorphism of IFN-γ is not related to periodontitis risk." (PMID 35046930, 2021). "In addition, no one has done a meta-analysis of the relationship between TNF-α-1031T/C, -857C/T gene polymorphism, and susceptibility to periodontitis." (PMID 32899013, 2020). "In addition, PGFE effectively regulated the expression of the pro-inflammatory cytokines IL-6, IL-1β, and TNF-α, which play an important role in the regulation of periodontitis in PG-LPS-stimulated HPDL cells, and it effectively suppressed the mRNA levels of these pro-inflammatory cytokines." (PMID 33287198, 2020). "In addition, one of the most important key factors responsible for periodontal destruction is the upregulation of inflammatory cytokines, including IL-1β, IL-6, and TNF-α, in the inflammatory sites of periodontal tissue; these cytokines are mainly involved in the pathogenesis of periodontitis." (PMID 33287198, 2020). "The most famous member of the family is TNF-α, which is a pro-inflammatory cytokine that contribute to acute and chronic inflammation and tissue injury, it could promote osteoclast activity, thus enhance bone resorption in periodontitis." (PMID 33289699, 2020). "In addition, TNF-α and IL-6 levels are higher in alcohol users, which might be equally in crevicular fluid, being related to the presence of periodontitis." (PMID 32730269, 2020). "In addition, treatment with a TNF-α antagonist could reduce sclerostin expression in osteocytes in diabetic rats with periodontitis." (PMID 31341915, 2019).
periodontitis (continued). "In addition, salivary BPIFA1 might reflect regulation of the inflammatory immune response in periodontitis subjects through the production of salivary TNF-α." (PMID 29109737, 2017). "Therefore, TNF-α might mediate alveolar bone loss via inducing expression of osteocytic RANKL and sclerostin in type 1 diabetes rats with periodontitis." (PMID 29240821, 2017). "Periodontitis is one of the most common chronic infectious diseases and is caused mainly by gram-negative microaerophilic and anaerobic bacteria that colonize the subgingival area and produce significant amounts of proinflammatory mediators, mainly IL-1β, IL-6, PGE2, and TNF-α." (PMID 28243243, 2017). "In addition, TNF-α inhibitor (TNF-αi), a chemosynthetic competitive antibody of TNF-α, could inhibit inflammatory bone resorption, when systemically administrated in an animal model of experimental periodontitis." (PMID 29250118, 2017). "Hyperparathyroidism increased ABL associated to periodontitis (0.99 ± 0.07 vs. 0.70 ± 0.008 mm, p < 0.001), as well as gingival levels of IL-1β and TNF-α (92.25 ± 6.26 vs. 68.25 ± 5.23 pg/mL for IL-1β, p < 0.01; and 80.73 ± 4.52 vs. 62.85 ± 5.85 pg/mL for TNF-α, p < 0.05)." (PMID 27617985, 2016). "Because the progression of periodontitis is closely related with the expression of inflammatory cytokines such as IL-1β, -6, -8 and TNFα in gingival tissues, ET-1 could play important roles in the initiation and progression of the disease through the regulation of cytokine expression." (PMID 28030574, 2016). "Periodontitis has been shown to be associated with a raised serum pro-inflammatory state as shown by increases in C Reactive Protein (CRP) and pro-inflammatory cytokines (e.g. Tumour Necrosis Factor α (TNFα)) with a reduction in anti-inflammatory markers (e.g. interleukin 10 (IL 10))." (PMID 26963387, 2016). "However, the presence of periodontitis at baseline was associated with a fall in serum IL10 levels, and serum baseline P. gingivalis antibody levels were also associated with a fall in serum IL10 levels and an increase in serum TNFα levels." (PMID 26963387, 2016). "Therefore, the aim of the present study is to compare periodontal parameter values and serum levels of IL‐6, sIL‐6R, soluble gp130 (sgp130), serum amyloid A (SAA), TNF‐α, IL‐17, and total immunoglobulin G (IgG) in patients with RA and periodontitis before and after TCZ therapy." (PMID 29744142, 2015). "In conclusion, the results of the present investigation suggest that anethole may have a potent inhibitory effect on periodontitis through suppression of pro-inflammatory molecules (i.e. IL-1β and TNF-α); therefore it could be a novel therapeutic strategy for periodontitis." (PMID 25587321, 2014). "However, excess TNF-α leads to dysregulated immune responses and progression of periodontitis." (PMID 25179218, 2014). "The detected in this study, following treatment with the probiotic strain of L. reuteri, decreased levels of TNF-α, IL-1β and IL-17 in periodontal pockets of patients with periodontitis may carry a clinical significance, preventing against progression of the disease." (PMID 24509697, 2014). "On the other hand, it has already been well documented that pathogenesis of chronic periodontitis may be determined by a pro-inflammatory response of cytokines, expressed in particular by secretion of tumor necrosis factor (TNF)-α, interleukin (IL)-1β and IL-17." (PMID 24509697, 2014). "However, the association of IL-10 and TNF-α SNPs with periodontitis in a subsequent investigation was not confirmed." (PMID 24274085, 2013). "As IL-1β and TNFα are two of the important pro-inflammatory cytokines that contribute to inflammatory connective tissue degradation in periodontitis, we determined whether matrix metalloproteinases (MMPs) and tissue inhibitors of MMPs (TIMPs) were stimulated or inhibited by these cytokines." (PMID 23940616, 2013).